MTOR (mechanistic target of rapamycin kinase)
Diseases named in the same sentence as MTOR in open-access papers (continued):
Sharing a sentence is not in itself a finding about the gene and the disease.
Insulin resistance (continued). "Interestingly, ER stress increases mTOR activity, whereas mTOR inhibition ameliorates ER stress-induced insulin resistance in myotubes." (PMID 35428325, 2022). "In that way, downregulation of mTOR seen in overweight T1DM could further aggravate processes leading to peripheral insulin resistance." (PMID 36042901, 2022). "Moreover, ICV injection of [D-Lys-3]-GHRP-6 significantly up-regulated the phosphorylation levels of PI3K/Akt/mTOR signaling protein expressions in the hypothalamus, indicating a significant improvement in hypothalamic insulin resistance." (PMID 36246070, 2022). "Obesity and WD also modulate mTOR signaling, which may exacerbate insulin resistance and other obesity‐related diseases." (PMID 36117462, 2022). "In addition, pigs with elevation blood level of selenium showed downregulation of INSR (insulin receptor) and upregulation of mTOR-s6, regarded as insulin resistance." (PMID 35975984, 2022). "Finally, in silico experiments, it was revealed that MGF affected autophagy-related mechanisms such as mTOR signaling pathways among the genes related to insulin resistance." (PMID 36499655, 2022). "This work further emphasizes the importance of the plasma metabolite PA and its interaction with innate insulin resistance within the context of the PYCR1 inhibition-mediated Akt/mTOR signalling involved in the manifestation of LDR + HFD-associated metabolic impairment." (PMID 36088469, 2022). "Based on gene count, we identified the top 29 pathways in the KEGG pathway enrichment analysis, which were associated with insulin resistance and inflammation, such as TNF signaling, PI3K-Akt signaling, MAPK signaling, HIF-1 signaling, estrogen signaling, cAMP signaling, and mTOR signaling pathways." (PMID 35052852, 2022). "Our results suggest that the EV originated from metabolic damage in β-cells may contribute to insulin resistance in hepatocytes by decreasing mTOR/p70S6Kα activation." (PMID 36005626, 2022). "Moreover, mTOR-stimulated pAkt activation in muscle with the consequent development of insulin resistance, solely occurred when BCAA were supplemented in combination with a high-fat diet, and not upon BCAA supplementation combined with chow." (PMID 35931683, 2022). "Increased circulating levels of BCAAs (i.e., Val, Leu, Ile) have also been related to insulin resistance through the BCAA-induced activation of the mechanistic target of rapamycin (mTOR) in the muscle and the direct toxicity of BCAA products, such as branched-chain ketoacids (BCKA)." (PMID 35736435, 2022). "The pathway analysis showed insulin resistance and mTOR as important pathways inhibited by CN03." (PMID 35241647, 2022). "Different protein intake could induce changes in some amino acids and other active substances in plasma, as well as related metabolic pathways such as the mTOR signaling pathway and FoxO signaling pathway, which may affect maternal insulin resistance." (PMID 36501068, 2022). "However, the beneficial effects of rapamycin remain coupled to toxicities that limit its broader clinical application, including insulin resistance and impaired wound healing, which result from on-target inhibition of mTOR." (PMID 36095197, 2022). "Moreover, ICV injection of [D-Lys-3]-GHRP-6 significantly up-regulated the phosphorylation of hypothalamic PI3K/Akt/mTOR signaling proteins, indicating a significant improvement in hypothalamic insulin resistance." (PMID 36246070, 2022). "Then, mTOR contributes to insulin resistance, inducing ER stress as well." (PMID 34069890, 2021). "However, a significant insulin resistance was observed at 12 weeks of HFD in mTOR-KOPlacenta compared with littermate controls." (PMID 34032632, 2021). "Together these data suggest that mTOR-KOPlacenta mice have increased susceptibility to glucose homeostasis dysfunction, in part, due to lack of β cell mass compensation for insulin resistance." (PMID 34032632, 2021).
Insulin resistance (continued). "Although both complexes of mTOR are involved in the pathogenesis of diabetes through their actions in β-cell metabolism and immune cells, the role of mTORC1 in insulin resistance and in the progression of T2D will be explained in more detail for a better understanding of type 3 diabetes (T3D)." (PMID 34069890, 2021). "Based on these findings, we conclude that miR-155-5p upregulation ameliorates chronic alcohol consumption-induced myocardial insulin resistance via the mTOR signaling pathway, which may provide a potential therapeutic target for ACM." (PMID 33868799, 2021). "The insulin resistance inhibited the phosphorylation of mTOR and inhibited myosin expression." (PMID 34676967, 2021). "First, insulin resistance, through inhibition of the mTOR pathway, activation of autophagy, activation of the ubiquitin-proteasome proteolytic pathway, and accelerated muscle protein degradation may cause sarcopenia." (PMID 35002965, 2021). "Metformin changed in phosphorylated mTOR proteins and serum markers of insulin resistance." (PMID 33917520, 2021). "Moreover, ablation of mTOR in adipocytes resulted in insulin resistance and fatty liver, and it appears that mTOR is required for the differentiation of adipocytes." (PMID 33806509, 2021). "Interestingly, BCAA-mediated mTOR activation and insulin resistance appears to be influenced by the background nutritional composition of the diet." (PMID 33923531, 2021). "Moreover, the mTOR signaling pathway regulates glucose metabolism and plays a crucial role in insulin resistance." (PMID 33868799, 2021). "Moreover, Aβ and insulin resistance suppress phosphatidylinositol-4,5-bisphosphate 3-kinase- (PI3K-) Akt signaling leading to activation of GSK-3β and mTOR, which in turn causes PP2A inhibition and subsequent tau hyperphosphorylation." (PMID 34306309, 2021). "Overall, our data demonstrated that miR-155-5p upregulation may protect against myocardial insulin resistance in chronic alcohol intake rats via the mTOR signaling pathway, which might provide a potential therapeutic target for ACM." (PMID 33868799, 2021). "PI3K/mTOR pathway inhibition also affects insulin signaling, resulting in insulin resistance." (PMID 34830886, 2021). "Insulin resistance seems to enhance or weaken mTOR gene expression." (PMID 32405346, 2020). "The frequent activation of mTOR has close relation with insulin resistance in patients and animals." (PMID 32698821, 2020). "Reduced mTOR signaling in the liver of Ptcd1+/- mice may be a way to protect liver function against the development of insulin resistance and metabolic dysfunction early in life." (PMID 33024056, 2020). "Similarly, p70 S6K, the downstream effector of mTOR, is implicated in the serine phosphorylation of IRS-1, leading to impaired insulin signaling and insulin resistance." (PMID 32664532, 2020). "Additionally, p70 S6K, the downstream effector of mTOR, has been shown to cause serine phosphorylation of IRS-1, resulting in impaired insulin signaling and insulin resistance." (PMID 32230718, 2020). "The side effects of mTOR inhibitors in transplanted patients, such as dyslipidemia, hyperglycemia, and insulin resistance, may explain the scarceness of progression in clinical studies." (PMID 32106480, 2020). "This study was undertaken to test our hypothesis that CaMKIV through decreased autophagy can suppress ER stress and improve insulin resistance by mTOR/CREB signaling." (PMID 32660483, 2020). "Indeed, while BCAA-induced activation of the mammalian target of rapamycin (mTOR) in skeletal myocytes may contrast sarcopenia and functional decline in advanced age, other studies found an association between higher circulating levels of BCAAs and insulin resistance or T2DM in older adults." (PMID 31940925, 2020). "The activation of the mTOR/S6 pathway in the liver may also contribute to the development of systemic insulin resistance." (PMID 31509973, 2019).
Insulin resistance (continued). "mTOR causes the serine/threonine phosphorylation of IRS by activating S6K, and reduces its ability to be phosphorylated on tyrosine residues, which results in impaired insulin signaling and insulin resistance." (PMID 31824416, 2019). "Conversely, hypothalamic mTOR/S6K pathway suppression reverses HFD-induced insulin resistance." (PMID 30875909, 2019). "Here, we first report that delivery of rapamycin or an adenovirus encoding the dominant negative acting mTOR-mutated protein into the upper small intestine is sufficient to inhibit small intestinal mTOR signaling and lower glucose production in rodents with high fat diet-induced insulin resistance." (PMID 30755615, 2019). "Increased Akt/mTOR signaling may contribute to the progression of steatosis in case of higher insulin levels in insulin resistance by inhibiting autophagy." (PMID 31509973, 2019). "The primary finding of the present study was that excitotoxic glutamate inhibits the IR/Akt/mTOR pathway, resulting in the development of acute neuronal insulin resistance during periods of significant mitochondrial depolarisation caused by glutamate-evoked massive influxes of Ca2+." (PMID 31856878, 2019). "The insulin resistance in Adipoq-mTOR mice might mainly result from hepatic steatosis induced by deletion of mTORC2 in adipose tissues 8,11." (PMID 30318987, 2019). "We hypothesize that galangin and pinocembrin may have a synergistic effect on the alleviation of insulin resistance via Akt/mTOR signaling pathway." (PMID 30420897, 2018). "Overall, we hypothesize that galangin and pinocembrin may synergistically relieve insulin resistance through regulating the protein phosphorylation of key Akt/mTOR signal proteins." (PMID 30420897, 2018). "Other mechanisms that explain insulin resistance are the activation of both mTOR and S6K1 pathways." (PMID 30170598, 2018). "Besides, the continuous activation of the neuronal PI3K/Akt/mTOR pathway has been related with the induction of insulin resistance in the AD brain." (PMID 30564080, 2018). "In turn, mTOR signaling dysregulation may facilitate the development of type 2 diabetes mellitus (T2DM) or insulin resistance." (PMID 30011848, 2018). "Of great interest, MCFA could effectively represent an interesting tool to manage insulin resistance, as they appear to potentiate the Akt-mTOR pathway in hepatocytes." (PMID 30208604, 2018). "Interestingly, recent evidence suggests that rapamycin, an inhibitor of mTOR, can block vaspin-mediated signals responsible for insulin resistance." (PMID 29240812, 2017). "Amino acid signaling may facilitate insulin resistance, by activation of the mammalian target of rapamycin (mTOR), a nutrient sensor that operates a detrimental feedback loop toward insulin receptor substrate 1 signaling." (PMID 28878172, 2017). "PI3K/Akt/mTOR signaling pathway is the pivotal pathway for regulating insulin resistance." (PMID 28491104, 2017). "As mechanistic target of rapamycin (mTOR) is activated by insulin signalling, and may also regulate autophagy, we also investigated whether mTOR signalling had any involvement in insulin-induced insulin resistance in podocytes." (PMID 28852804, 2017). "In addition, feeding animals with BCAAs induced insulin resistance, along with the chronic phosphorylation of mTOR, JNK, and IRS1Ser307." (PMID 26788116, 2016). "Therefore, we evaluated the insulin resistance and mTOR signaling protein levels in skeletal muscle of high fat diet induced obese rats after 8 weeks of regular exercise and dietary change." (PMID 27508151, 2016). "We also emphasized on the need for prudent mTOR targeting to ameliorate insulin resistance." (PMID 27826244, 2016). "The present study investigated whether rapamycin, a specific inhibitor of mTOR, ameliorates inflammatory stress-induced insulin resistance in vitro and in vivo." (PMID 26449763, 2015).
Insulin resistance (continued). "mTOR activation oversees stem cell development, fosters pancreatic β-cell proliferation, limits insulin resistance, and can prevent pathways that may lead to atherosclerosis." (PMID 26064426, 2015). "Therefore, excessive mTOR/S6K1 activation by either amino acids or insulin leads to insulin resistance." (PMID 26007339, 2015). "Treatment with the mTOR inhibitor rapamycin did not affect AMPK phosphorylation; however, incubation with two distinct AMPK activators, AICAR and alpha lipoic acid, prevented both the insulin resistance (impaired insulin-stimulated Akt phosphorylation) and mTOR/p70S6K phosphorylation." (PMID 25996822, 2015). "Insulin resistance is also induced by mTOR/S6K1 pathway overactivation." (PMID 26007339, 2015). "Our study showed that a causal association was unlikely, but there is increasing evidence that dietary protein intake, under isoenergetic conditions, may indeed increase insulin resistance via activation of the mTOR/S6K1 signaling pathway." (PMID 24870294, 2014). "mTOR signaling is overactivated in obesity, promoting inflammation and insulin resistance." (PMID 24710396, 2014). "mTOR signaling pathway is constitutively activated in obesity, leading to insulin resistance." (PMID 24710396, 2014). "For example, high-dose leucine infusion and supplementation have been shown to induce insulin resistance and glucose intolerance in both human and animal models, possibly via activation of mammalian target of rapamycin- (mTOR-) insulin receptor substrate 1 (IRS-1) signaling pathways." (PMID 25400942, 2014). "Our data suggest evodiamine improves glucose tolerance and prevents progress of insulin resistance associated with obese/diabetic states, at least in part, through AMPK activation followed by inhibition of mTOR-S6K signaling and IRS1 serine phosphorylation in adipocytes." (PMID 24391749, 2013). "This increases RhoA/ROCK signaling and chronic mTOR activation resulting in insulin resistance." (PMID 23776620, 2013). "In humans, infusion of amino acids activate mTOR/S6K1, causing insulin resistance." (PMID 22683661, 2012). "As a result, activation of the mTOR pathway in the cardiovascular system may lead to poor insulin signaling and insulin resistance." (PMID 22545721, 2012). "Resistin also phosphorylates IRS1 through mTOR to promote insulin resistance." (PMID 22545721, 2012). "Other serine/threonine kinase activated in high-fat diet-induced or palmitate-induced insulin resistance is mammalian target of rapamycin (mTOR), but the mechanisms involved are unknown yet." (PMID 22360800, 2012). "Thus,the activity state of the mTOR pathway can modulate insulin sensitivity inhumans and mTOR inhibitors prevent nutrient-induced insulin resistance." (PMID 20157523, 2009). "However, chronically elevated fasting plasma concentrations of BCAAs, under conditions of nutrient excess and hyperinsuliunemia, have been linked to overactivation of mTOR and S6K1 pathways, which may lead to systemic insulin resistance." (PMID 41190149, 2025). "However, the inhibition of PI3K/AKT/mTOR by small molecule inhibitors may lead to insulin resistance in cancer cells, posing a significant challenge that could worsen disease outcomes." (PMID 39410536, 2024). "MTOR is known to regulate the adaptation of beta cells to blood glucose, and dysregulation in mTOR signaling may facilitate the development of type 2 diabetes or insulin resistance." (PMID 37569434, 2023). "Thus, p62 in muscle may promote skeletal muscle protein synthesis by activating mTOR and ameliorate insulin resistance via the AKT-GLUT4 pathway." (PMID 36439272, 2022). "Of note, Astragaloside IV, a natural saponin extracted from AM, was unfolded to attenuate liver injury in type 2 diabetes by regulating the AMP-activated protein kinase (AMPK)/mammalian target of rapamycin (mTOR)/autophagy pathway, which could alleviate insulin resistance and dyslipidemia." (PMID 35267929, 2022).
Insulin resistance (continued). "Hence, a dysregulation of the BVR-A/AMPK axis may have a role in mTOR-mediated brain insulin resistance development." (PMID 35628384, 2022). "In addition, several studies found that simvastatin induced insulin resistance by suppressing Akt/mTOR signalling pathway, which affects the GLUT4 translocation into the membrane, which may then reduce glucose uptake into the muscle cells (L6 and C2C12)." (PMID 36235772, 2022). "Interestingly, blockade of ghrelin receptor could take care of MAFLD, possibly via the hypothalamic PI3K/AKT/mTOR signaling, to improve insulin resistance." (PMID 36671395, 2022). "However, it is unknown whether miR-155 exerts a protective effect against ethanol-induced myocardial insulin resistance via the mTOR signaling pathway." (PMID 33868799, 2021). "However, constitutive activation of the Rheb/mTOR/S6K pathway can induce a negative feedback and thus cause insulin resistance." (PMID 34419103, 2021). "Therefore, mTOR/4E-BP1 signaling pathway may participate in the regulation of autophagy-mediated insulin resistance." (PMID 32698821, 2020). "Besides these neuroprotective actions, in the Ts65Dn mouse, this inhibition of mTOR signaling after rapamycin administration also prevented the abnormal autophagy and recovered the insulin resistance pathway, thereby decreasing brain insulin resistance." (PMID 32756318, 2020). "Although the exact molecular link between insulin resistance and glutamate excitotoxicity remains elusive, it has been suggested that the excitotoxic glutamate may induce the development of neuronal insulin resistance via inhibiting the IR/Akt/mTOR pathways." (PMID 32971941, 2020). "In turn, mTOR and p70S6K are enzymes that integrate many cell signaling pathways, including the insulin one, the dysregulation of which may be involved in the pathogenesis of insulin resistance and type 2 diabetes." (PMID 32917052, 2020). "Therefore, we hypothesize that mTOR may function as a key target by connecting psoriasis and MetS through insulin resistance." (PMID 31824416, 2019). "However, many studies now confirm that activation of the mTOR/S6K1 kinase signaling pathway is not a sufficient condition to cause insulin resistance." (PMID 31481892, 2019). "In order to verify if the altered mTOR and FoxO1 pathways could contribute to skeletal muscle atrophy in DM and T2DM patients i.e. those patients who showed insulin resistance, we analysed the correlation of mTOR, FoxO1, MuRF1 and Atrogin-1/MAFbx expressions with atrophy factors." (PMID 30901379, 2019). "In addition, Akt/mTOR signaling pathway is involved in insulin resistance." (PMID 29552281, 2018). "Thus, the loss of estrogen and its receptors can further contribute to the dysregulation of signaling and both too much and too little estrogen can contribute to insulin resistance, and aberrant mTOR activation, starting early in life, and continuing through reproductive senescence." (PMID 29988365, 2018). "However, it remains unclear whether propolis flavonoids ameliorate insulin resistance via Akt/mTOR signaling pathway." (PMID 30420897, 2018). "Thus, insulin resistance suppresses podocyte autophagy through increasing the activity of mTOR." (PMID 28512641, 2017). "Thus it has been suggested that mTOR inhibitors might offer therapeutic benefits in metabolic diseases such as insulin resistance and obesity." (PMID 29077002, 2017). "In addition, the precise mechanisms by which exercise and/or dietary change affect upstream and downstream mTOR signaling pathway related in insulin resistance is currently unknown." (PMID 27508151, 2016). "In addition, we found that all of the changes, including increases in mTOR/p70S6K phosphorylation and protein synthesis, in addition to the insulin resistance, could be prevented by co-incubation with the AMPK activator AICAR." (PMID 25996822, 2015).